VEGFA (vascular endothelial growth factor A)
Diseases named in the same sentence as VEGFA in open-access papers (continued):
Sharing a sentence is not in itself a finding about the gene and the disease.
tumor (continued). "We also found activation of biological pathways, including VEGFA and WNT signalling, and abnormal activity of several genes linked to immune therapy response, with marked variation between tumour regions." (PMID 41168392, 2025). "CDK6 specifically regulates the transcription of tumor-related genes such as vascular endothelial growth factor-A (VEGF-A) and early growth response gene-1 (EGR1), thereby promoting the transcription of genes from G1 to S phase." (PMID 39944826, 2025). "VARGG accurately reveals the spatial organization of tumors and identifies key genes related to tumor progression and immune microenvironment (VEGFA, CD74, SPP1, IGFBP5, TIMP2, EMP1, THY1)." (PMID 41275376, 2025). "TAMs involve in tumor angiogenesis by secreting several pro-angiogenic cytokines, including VEGFA, platelet-derived growth factor β (PDGF-β), angiogenin, placental growth factor (PlGF), TGF-β, and MMPs." (PMID 40443670, 2025). "Vascular endothelial growth factor-A (VEGF-A), produced by tumor cells, binds VEGFR2 on endothelial cells, thereby activating the PI3K/Akt and ERK1/2 pathways to promote aberrant angiogenesis." (PMID 40958866, 2025). "The overexpression of VEGFA has been observed in many cancers, including HCC, and is associated with poor prognosis and increased tumor aggressiveness." (PMID 39852395, 2025). "HIF-1α activation boosts VEGFA mRNA and protein expression in hypoxic endothelial, stromal, and tumor cells, leading to VEGFR2 stimulation in adjacent cells." (PMID 41150799, 2025). "A limitation of current study is that only syngenetic tumor models were investigated to permit assessment of the bispecific strategy targeting both tumor and host-derived VEGFA in an immunocompetent host." (PMID 40906526, 2025). "For example, secretion of VEGFA promotes angiogenesis and tumor growth, IL6 activates the STAT/JAK1 pathway enhancing cancer cell plasticity, and TGF‐β induces EMT, cell invasion capacity and resistance to treatment." (PMID 40411295, 2025). "This transcription factor also promotes tumor angiogenesis by upregulating various angiogenic factors like VEGFA by binding at the HRE sequence present at their promoter region of genes." (PMID 40045186, 2025). "Cancer-related genes, such as CD70, VEGFA, and ENTPD1 (also known as CD39), which are reportedly associated with immune suppression, tumor proliferation, immune escape, and drug resistance, exhibited increased expression in patients in the neural-high group." (PMID 41147013, 2025). "In this study, calcitriol upregulated miR-382-5p in CaSki cells, potentially reducing VEGFA expression and its tumor-promoting activity." (PMID 40168262, 2025). "In conclusion, SPHK1/S1P axis is hyperactivated in CRC patients with poor prognosis and promotes angiogenesis by increasing VEGFA expression in both tumor cells and M2 macrophages." (PMID 40589755, 2025). "Clinical analyses further reveal a positive correlation between VEGFA expression and RBM15/IGF2BP3/YTHDF2 levels, underscoring the central role of RBM15-mediated m6A modification in VEGFA regulation and tumor angiogenesis." (PMID 41403702, 2025). "According to the same study results, PRAT area expansion has been associated with VEGFA, JAG1, and TGF-β1 pro-angiogenesis gene expression increases, suggesting a possible interplay between PRAT-derived leptin activity and tumor angiogenesis." (PMID 40227577, 2025). "This molecular profile is consistent with the observed increase in angiogenesis and vessel calibre in PAK4KO tumours, suggesting that the PAK4 knockout enhanced VEGF-associated signalling, despite a reduced VEGFA expression in these cells." (PMID 41294859, 2025). "Vascular endothelial growth factor A (VEGFA) is one of the primary factors driving expansion of the tumor vascular bed." (PMID 38429756, 2024). "WB analysis confirmed a significant reduction in VEGFA expression in xenograft tumor with circSNX6 silencing (P < 0.05)." (PMID 38589413, 2024).
tumor (continued). "For example, MDSCs, as critical molecules in PMN formation, can produce VEGFA, which upregulates E-selectin, thereby enhancing the adhesion of tumor cells, and facilitating the homing and proliferation of circulating tumor cells." (PMID 38571500, 2024). "Knockdown of VEGFA substantially reversed the impact of miR‐378a‐3p inhibitor on tumor growth and the epithelial‐mesenchymal transition (EMT) process." (PMID 39606802, 2024). "In in vivo experiments, elevated circulating levels of TMAO in tumor-bearing mice lead to a significant increase in tumor volume, new blood vessel formation, and the quantities of VEGFA and CD31." (PMID 39710789, 2024). "Despite the potential of bevacizumab, a monoclonal antibody targeting VEGFA to disrupt tumor angiogenesis, it faces challenges and limitations in treatment outcomes." (PMID 39063226, 2024). "Bevacizumab is a therapeutic monoclonal antibody designed to modulate tumor angiogenesis by inactivating vascular endothelial growth factor A (VEGF-A)." (PMID 38327681, 2024). "Bevacizumab binds to circulating VEGFA, hindering its interaction with VEGFRs on endothelial cell surfaces, thereby impeding crucial steps in tumor blood vessel formation." (PMID 38716237, 2024). "The TNF+/VEGFA+ ratio was high in adjacent normal tissues (ratio=4), which was lower than that in tumor tissues, with the lowest ratio occurring at the tumor rim (ratio=1.2)." (PMID 39840068, 2024). "Because of the pronounced pro-angiogenic effects of VEGFA, high VEGFA expression exacerbates tumor vascular abnormalities, poor perfusion, and inadequate oxygen supply." (PMID 38532022, 2024). "Our study demonstrates that EVs derived from CRC cells promote tumor angiogenesis by regulating the JAK/STAT3/VEGFA pathway in endothelial cells." (PMID 39596828, 2024). "A reduction in secretion of angiogenic factors such as VEGFA with impaired tumor angiogenesis was observed." (PMID 39021040, 2024). "This upregulation of VEGFA leads to new blood vessel formation, which is crucial for tumor growth, and a higher microvessel density correlates with poorer patient survival." (PMID 39063226, 2024). "Platelets also promote tumor metastasis and angiogenesis by releasing various growth factors, such as vascular endothelial growth factor-A, and can promote immune evasion and chemoresistance in tumor cells." (PMID 39512347, 2024). "AML-MSCs have been found to have high levels of VEGFA and IL-6, which contribute to tumour-supportive angiogenesis." (PMID 39200142, 2024). "The experimental condition of KrasG12V mutation observed that the primary tumor activated the downstream RAS-effector factor AKT, β5 integrin, and overexpression of vascular endothelial growth factor A (VEGFA) and serpin-1." (PMID 39056802, 2024). "Beyond angiogenesis, VEGFA also controls the behavior of BC cells and other cells in the tumor microenvironment." (PMID 38321003, 2024). "Vascular endothelial growth factor (VEGFA), a key protein in tumor angiogenesis, is a critical downstream target of HIF1α signaling and plays an important role in tumor invasion and metastasis." (PMID 38339062, 2024). "High stiffness also led to increased vascular endothelial growth factor A (VEGFA), matrix metalloproteinases (MMP) and CD206 expression; ‘M2’ markers expressed by tumor–associated macrophages (TAMs)." (PMID 39211033, 2024). "For example, VEGFA (Vascular Endothelial Growth Factor A) is a well-known mediator of angiogenesis, critical for tumor growth and metastasis." (PMID 39684488, 2024). "The interaction between RGC‐32 and VEGFA was validated, and the positive correlation of their expression in the tumor tissues were also validated." (PMID 39606802, 2024). "A similar effect of Smad2 on tumor angiogenesis was reported in breast cancer cells, in which Smad2 suppressed the expression of vascular endothelial growth factor A, a crucial promoter of tumor angiogenesis." (PMID 38569937, 2024).
tumor (continued). "The tumor immune suppression in the tumor microenvironment (TME) was also suppressed by decreasing vascular endothelial growth factor A (VEGF-A) protein levels." (PMID 39138299, 2024). "In HCC, VEGFA is essential to the development and spread of tumors by promoting angiogenesis, facilitating tumor vascularization, and enhancing tumor cell survival." (PMID 39319846, 2024). "The discovery of VEGF led to a major step forward in understanding angiogenic pathways; in 1993, Kim and colleagues identified mAbs that were able to target and neutralize VEGFA, thereby inhibiting tumor growth in preclinical studies." (PMID 38339258, 2024). "IRE1 and PERK/ATF4 showed pivotal for the activation of VEGFA and other pro‐angiogenic genes in response to hypoxia and hypoglycemia relative to tumor ischemia." (PMID 39021040, 2024). "Analysis of spatial interactions of VEGF+/– macrophages to CD34+ endothelial cells in HCC tumor tissue from these 8 patients identified that VEGFA+ and VEGFA– macrophages preferentially reside 0–20 μm from CD34+ endothelial cells." (PMID 39761010, 2024). "Hypoxia-induced increase in VEGFA levels in the tumor microenvironment correlates with disintegration of VE-cadherin junctions and dismantling of the blood vascular barrier." (PMID 38148112, 2024). "Among many angiogenic factors, VEGFA has been identified as the key driver of neovascularization in HCC, with tumor cells largely implicated in its production." (PMID 39761010, 2024). "According to the findings, oe-ZBTB7A cell-derived tumour masses had much lower positive rates for KI-67, CD31, and VEGFA than oe-NC-derived tumours." (PMID 38981872, 2024). "In IDO1-SOE mice, serum KP activity and VEGFA concentration were increased accompanied by a rise in the expression of CD34, ATF4, IDO1, and VEGFA in tumor tissues, with the most significant uplift observed in ATF4 and IDO1 expression." (PMID 39065567, 2024). "Analysis based on tumour grade using the UALCAN portal revealed specific expression patterns such as increased VEGFA expression in grade 2 and grade 3 tumours, elevated VEGFB expression in grade 3 tumours and high KDR expression in grade 4 tumours." (PMID 38426619, 2024). "Studies have shown that VEGFA and bFGF increase vascular permeability and are involved in physiological and tumor-induced vascularization." (PMID 38173775, 2024). "Vascular endothelial growth factor A (VEGFA), a key angiogenic factor, is an important tumor-specific factor in RCC patients and plays a crucial role in tumor angiogenesis and progression." (PMID 38416262, 2024). "ISS on a tumor section spanning several mm2 identified nine hypoxic regions with focal VEGFA expression amid cellular tumor regions." (PMID 38123840, 2024). "VEGFA is a key pro-angiogenic ligand, and highly expressed VEGFA often stimulates angiogenesis and growth and is involved in tumor angiogenesis and metastasis." (PMID 38837097, 2024). "The combined inhibition of PGF and VEGFA exerts a synergistic effect on suppressing tumor growth and angiogenesis." (PMID 39628692, 2024). "In order to investigate the effects of anlotinib on inflammatory factors within xenograft tumors, we examined the expression of IL-6, IL-8 and VEGFA in tumor tissues of four treatment groups by immunofluorescence staining." (PMID 39193386, 2024). "In contrast to the pro-angiogenic effects of TGF-β in tumor cells, we observed that loss of TGF-β signaling in ECs led to increased expression of VEGFA and angiopoietin-1, suggesting distinct mechanisms within the endothelial compartment." (PMID 39758992, 2024). "VEGFA is one of the angiogenic factors widely involved in the regulation of tumor angiogenesis and progression." (PMID 37727135, 2024). "In BCa, METTL3 regulates the PI3K/AKT pathway associated with tumor angiogenesis and promotes tumor angiogenesis by modulating TEK and VEGFA." (PMID 39295872, 2024).
tumor (continued). "TAN promotes blood vessel growth and promotes tumor invasion and metastasis through various proangiogenic factors, such as VEGFA, and matrix metalloproteinase-9 (MMP-9)." (PMID 39132507, 2024). "This heightened level can enhance tumor cell proliferation, invasion, and metastasis by promoting the expression of vascular endothelial growth factor A (VEGFA) and angiogenesis." (PMID 38304430, 2024). "In this study, it has also been found that the expression of CD31 and VEGFA in 4T1 tumor tissues was inhibited by garlic peel extract and was positively correlated with the expression of COX‐2, which is consistent with the findings of previous studies." (PMID 39554336, 2024). "As cancer growth requires angiogenesis to supply nutrients to cancer cells, vascular endothelial growth factor A (VEGF-A) is produced in the tumor microenvironment, promoting vascular endothelial proliferation and angiogenesis." (PMID 38534624, 2024). "SPP1+VEGFA+ TAM were also trending towards increased proportions in tumor samples (Diff = 3.4%, p-value = 0.21)." (PMID 39075108, 2024). "This is evident in bevacizumab’s capacity to induce direct cytotoxic effects in various tumor cells expressing high VEGFA levels." (PMID 38716237, 2024). "Here, we showed that ID4 protein expression in BC contributes to tumor aggressiveness stimulating cell migration and invasion by regulating VEGFA production." (PMID 38321003, 2024). "Tumor angiogenesis is supported by TAMs primarily through the production of factors such as VEGFA, PDGF, PIGF, FGF, and TGF-β." (PMID 38957393, 2024). "The risk score strongly correlated with the expression of VEGFA, VEGFB, CD276 and C10orf54, and each immune checkpoint was differentially expressed between normal and tumour samples." (PMID 38613352, 2024). "VEGFA is a key promoter of both tumor angiogenesis and immunosuppression, and is an attractive target for combinatorial cancer therapy." (PMID 39457009, 2024). "VEGFA is involved in tumor angiogenesis and metastasis, and VEGFA inhibitor bevacizumab has been approved by FDA for the targeted therapy of CRC." (PMID 38818308, 2024). "Humanized monoclonal antibodies were developed to inhibit tumor neo-angiogenesis, which is driven by VEGFA/KDR signaling." (PMID 39000466, 2024). "Further, curcumin downregulated the gene expression of factors secreted by tumor cells known to induce immunosuppression (VEGFA, PDGF, IL4, OSM, CXCR4 and Fas ligand)." (PMID 39861845, 2024). "The results showed that the combination of emodin and ALA‐PDT significantly inhibited the expression of VEGFA to inhibit angiogenesis (p < 0.001), thus showing an inhibitory effect on tumour (p < 0.001)." (PMID 39351642, 2024). "VEGFA, a key regulator of vascular remodeling and angiogenesis, was predominantly expressed in GBM neoplastic cells rather than vascular cells, suggesting potential paracrine signaling between VEGFA-secreting tumor cells and OR51E1-positive pericytes." (PMID 39769144, 2024). "Our result demonstrates that tumor cell-derived VEGFA contributes to M2 polarization of macrophages in TNBC." (PMID 38169627, 2024). "In conclusion, our data suggest that VEGFA acts as a hotspot in the reciprocal crosstalk between tumor cells and TAMs." (PMID 38169627, 2024). "Protumorigenic factors associated with hypoxia and angiogenesis, like HIF1A and VEGFA, as well as genes related to a pro-tumoral phenotype, such as SPP1 and TGFB2, were highly expressed in this macrophage found in the tumor context." (PMID 38972873, 2024). "Once bevacizumab suppresses VEGFA within the tumor microenvironment, it affects the tumor’s ability to access oxygen and nutrients, not only through reduced vasculature but potentially by exerting direct survival pressures on the tumor cells." (PMID 38716237, 2024). "VEGFA is often overexpressed in solid tumors and malignant diseases, significantly promoting tumor angiogenesis." (PMID 39274982, 2024).
tumor (continued). "Remarkably, the mRNA level of VEGFA positively correlated with that of GOLM1 in primary tumor tissues derived from HCC patients (R = 0.4724)." (PMID 39022745, 2024). "The results revealed the downregulation of E-cadherin, coupled with the upregulation of vimentin and VEGFA in tumor tissues of patients exhibiting osimertinib resistance, compared with those in tissues from patients before receiving osimertinib." (PMID 39375945, 2024). "Zippering of VE-cadherin junctions was established in dermal initial lymphatic vessels after VEGFA injection and in tumor-proximal lymphatics in mice." (PMID 38148112, 2024). "In the tumor microenvironment, Vascular Endothelial Growth Factor A (VEGF-A) drives tumor angiogenesis, leading to endothelial anergy and vascular immunosuppression—a state where ECs resist cytotoxic CD8+ T cell infiltration, hindering immune surveillance." (PMID 39337337, 2024). "HIF-1α and c-Myc interact to promote the expression of the VEGFA gene, which then drives pathological tumor angiogenesis." (PMID 39267840, 2024). "Bevacizumab, a monoclonal antibody targeting vascular endothelial growth factor (VEGF) alpha (VEGFA), disrupts tumor angiogenesis." (PMID 39063226, 2024). "Hypoxia can amplify the expression of CCL28, attracting CCR10-positive Treg cells into the tumor, suppressing the Teffs function, and also elevating the levels of VEGFA in the TME." (PMID 38500876, 2024). "Bevacizumab is a humanized monoclonal antibody that, by binding to VEGFA, inhibits the activation of its receptor and thus reduces tumor neo-angiogenesis." (PMID 39702370, 2024). "In the case of ccRCC, this results in a highly angiogenic tumour due to overproduction of hypoxia inducible VEGFA mRNA." (PMID 38352889, 2024). "In summary, VEGFA plays a crucial role in regulating angiogenesis and impacting the tumor microenvironment, thereby facilitating the onset and advancement of tumors." (PMID 38687357, 2024). "As a recognized serum biomarker for tumor diagnosis, GP73 is also highly expressed in tumors, where it boosts the expression and secretion of pro-inflammatory cytokines and vascular endothelial growth factor A (VEGFA) in tumor cells." (PMID 39845976, 2024). "VEGFA is essential for initiating the development of immature vessels within tumors, which is a critical step in tumor angiogenesis." (PMID 38994952, 2024). "Expression of VEGF C or VEGFA by different cell types in the tumor correlates with increased intratumoral lymphangiogenesis and lymph node metastasis." (PMID 38148112, 2024). "Under the influence of CXCL1/MIP-2, they release the vascular endothelial growth factor A (VEGF-A), through which they modulates tumor growth." (PMID 39408564, 2024). "The effect above stabilizes HIF-1α, promoting VEGFA transcription and secretion, resulting in angiogenesis in the tumor microenvironment." (PMID 39845976, 2024). "As anticipated, VEGFA was high for proximal tubule cells on tumor FOV, while stromal FOV showed lower expression in proximal tubule cells." (PMID 39639369, 2024). "Secretion of vascular permeability factor and vascular endothelial growth factor-A (VEGF-A) from tumoral cells is one of the main factors of angiogenesis." (PMID 38410788, 2024). "qPCR and WB were used to assess VEGFA and SerRS expression in tumour tissues across treatment groups." (PMID 39351642, 2024). "Bevacizumab was the first recombinant humanized murine IgG1 monoclonal antibody capable of blocking the activity of the Vascular Endothelial Growth Factor A (VEGF-A), a natural ligand that plays a pivotal role in tumor angiogenesis." (PMID 38365745, 2024). "Neovessel formation is typically stimulated by an excessive release of the vascular endothelial growth factor-A (VEGF-A) from hypoxic tumor cells." (PMID 38164270, 2024).